GCKR (glucokinase regulator)
Description:
Regulates glucokinase (GCK) by forming an inactive complex with this enzyme. Acts by promoting GCK recruitment to the nucleus, possibly to provide a reserve of GCK that can be quickly released in the cytoplasm after a meal. The affinity of GCKR for GCK is modulated by fructose metabolites: GCKR with bound fructose 6-phosphate has increased affinity for GCK, while GCKR with bound fructose 1-phosphate has strongly decreased affinity for GCK and does not inhibit GCK activity.
Synonyms: GKRP; FGQTL5
Target class: Enzyme
Safety:
Unwanted effects reported when the protein is acted on. In parentheses: how it was acted on, where the effect was seen, and who reports it.
alcoholism (source: ClinPGx)
Gene: Protein-coding gene on chromosome 2 (27,496,532 to 27,523,688, forward strand). Ensembl gene ENSG00000084734.
Subcellular location: Cytoplasm; Nucleus; Mitochondrion
Subcellular location (Human Protein Atlas): Nucleoplasm; Cytosol; Nucleoli
Pathways (Reactome):
Disease: Defective TPR may confer susceptibility towards thyroid papillary carcinoma (TPC)
Metabolism: Regulation of Glucokinase by Glucokinase Regulatory Protein
Genetic constraint (gnomAD): Loss-of-function variants: 45 observed, 50.7 expected, observed/expected ratio (o/e) 0.89, 90% interval 0.7 to 1.14. The upper end of that interval is the gene's LOEUF score, 1.14, which puts it in group 4 of 6, group 1 being the genes least tolerant of losing a copy. Missense variants: 592 observed, 603.21 expected, observed/expected ratio (o/e) 0.98, 90% interval 0.92 to 1.05. Synonymous variants: 223 observed, 230.67 expected, observed/expected ratio (o/e) 0.97, 90% interval 0.87 to 1.08.
Homologues: Orthologues: chimpanzee GCKR (99% identical), macaque GCKR (98% identical), dog GCKR (91% identical), rabbit GCKR (91% identical), pig GCKR (90% identical), rat Gckr (88% identical), guinea pig GCKR (88% identical), mouse Gckr (88% identical), tropical clawed frog gckr (57% identical), zebrafish gckr (19% identical).
Diseases named in the same sentence as GCKR in open-access papers:
GCKR is named in the same sentence as 104 diseases in open-access papers, as found by Europe PMC text mining. Sharing a sentence is not in itself a finding about the gene and the disease. The quoted sentences say what the papers report.
type 2 diabetes (64 papers, 2009 to 2026). "SNP rs1260326, a missense variant for gene GCKR, is known to be associated with alcohol intake, type 2 diabetes, liver diseases, and lipid levels such as triglycerides and cholesterol." (PMID 40865610, 2025). "Elevated GCKR levels were also associated with higher risk of type 2 diabetes (OR = 2.183, 95% CI = 1.846–2.581, p = 6.53 × 10−20)." (PMID 39921581, 2025). "The rs780094 variant in the GCKR gene is linked to several health conditions, including type 2 diabetes, metabolic syndromes, dyslipidemia, and their related traits." (PMID 38918799, 2024). "More importantly, as reported at genecards.org (accessed on 22 November 2022), diseases associated with GCKR include “fasting plasma glucose level quantitative trait locus 5 and maturity-onset diabetes of the young”, which is a severe issue in the young." (PMID 38666857, 2024). "The common human GCKR rs1260326:Pro446 > Leu variant within a large linkage disequilibrium region associates with pleiotropic traits including lower Type 2 diabetes risk and raised blood triglycerides and cholesterol." (PMID 37031802, 2023). "This was later corroborated by a larger effect of the GCKR variant on blood and liver triglycerides in obesity and type 2 diabetes." (PMID 37031802, 2023). "Several variants affect NAFL and blood lipids in the same direction, including p.Leu446Pro in GCKR, which also decreases glycated hemoglobin and type 2 diabetes risk." (PMID 36280732, 2022). "The rs780094 SNP within GCKR gene was associated with liver fat accumulation, increased triglyceride concentrations, reduced insulin levels, and reduced risk of type 2 diabetes." (PMID 35333773, 2022). "GCKR encodes for a glucokinase regulatory protein (GCKR), which modulates the metabolic syndrome-related traits, such as triglyceride levels, blood pressure, and type-2 diabetes risk." (PMID 33810064, 2021). "GCKR, a hub gene identified simultaneously by the susceptibility variants of alcohol consumption and type 2 diabetes, has densely interacted with type 2 diabetes-related genes such as FTO and SLC2A2." (PMID 34830198, 2021). "In a recent study, both rs1260326 and rs780094 in GCKR were shown to be functional variants associated with type 2 diabetes and metabolic syndrome in a European population." (PMID 29777116, 2018). "We previously demonstrated that the effects of the GCKR effect allele on plasma lipid levels were more pronounced in patients with type 2 diabetes when compared to healthy individuals." (PMID 30352097, 2018). "A similar interaction between GCKR and type 2 diabetes on CAD risk would seriously decrease the applicability of small molecule disruptors of the glucokinase-GKRP complex as new antidiabetic drug." (PMID 30352097, 2018). "Genetic variation in both GCK and GCKR has been implicated in type 2 diabetes susceptibility, and the proteins are both targets of ongoing drug development efforts to modulate this pathway." (PMID 28447115, 2017). "Recent genetic and clinical evidence has implicated glucokinase regulatory protein (GKRP) in the pathogenesis of type 2 diabetes and related traits." (PMID 24586696, 2014). "In Chinese, the association of GCKR variants with glucose, insulin, insulin resistance and the risk of type 2 diabetes was inconsistent with Europeans." (PMID 23383164, 2013). "Several studies of the association of GCKR variants with type 2 diabetes or glucose homeostasis parameters in Chinese populations have been reported." (PMID 21569451, 2011). "Several studies have shown that variants in the glucokinase regulatory protein gene (GCKR) were associated with type 2 diabetes and dyslipidemia." (PMID 21569451, 2011). "Of the previously known genes associated with type 2 diabetes (T2D), variants in GCKR and TCF7L2 were confirmed to be associated with 2 h BG." (PMID 21789219, 2011).
type 2 diabetes (continued). "We demonstrated that the rs3817588 A/G polymorphism of the GCKR gene was associated with type 2 diabetes and plasma triglyceride level in the Han Chinese population." (PMID 21569451, 2011). "The associations of GCKR rs780094 with type 2 diabetes and triglyceride level have been replicated in many studies of different ethnic populations since the Diabetes Genetics Initiative genome-wide association study." (PMID 21569451, 2011). "Rs780094 is tightly linked with rs1260326 (HapMap CEU r2 = 0.93, CHB r2 = 0.82), a non-synonymous variant in GCKR associated with type 2 diabetes and triglyceride level." (PMID 21569451, 2011). "The mechanism by which the GCKR variants lead to type 2 diabetes and protect against dyslipidemia remains to be determined." (PMID 21569451, 2011). "We investigated the association of polymorphisms in the GCKR gene with type 2 diabetes by employing a case-control study design (1118 cases and 1161 controls)." (PMID 21569451, 2011). "The G alleles of GCKR rs3817588 and rs780094 were associated with an increased risk of type 2 diabetes after adjustment for year of birth, sex and BMI (OR = 1.24, 95% CI 1.08-1.43, p = 0.002 and OR = 1.22, 95% CI 1.07-1.38, p = 0.002, respectively)." (PMID 21569451, 2011). "Our data showed that the GCKR rs780094 G allele and rs3817588 G allele were associated with an increased risk of type 2 diabetes in Han Chinese individuals." (PMID 21569451, 2011). "The rs3817588 A/G polymorphism of the GCKR gene was associated with type 2 diabetes and plasma triglyceride level in the Han Chinese population." (PMID 21569451, 2011). "The aim of this study was to replicate the associations of GCKR variants with type 2 diabetes and related traits found in Caucasian populations in a Han Chinese population and to identify the potential mechanisms underlying these associations." (PMID 21569451, 2011). "In the present study, the G allele of GCKR rs780094 was associated with higher odds of type 2 diabetes (OR = 1.19)." (PMID 21569451, 2011). "In conclusion, we showed that GCK, G6PC2 and MTNR1B variants modulated fasting glucose levels while G6PC2 and GCKR variants were associated with type 2 diabetes in the Shanghai Chinese." (PMID 20668700, 2010). "Associations of GCK rs1799884 and GCKR rs780094 with type 2 diabetes related traits in Chinese control subjects." (PMID 20628598, 2010). "They found GCK rs1799884 was associated with high fasting glucose while GCKR rs780094 was associated with high triglyceride level and type 2 diabetes." (PMID 20668700, 2010). "We showed that SNPs from GCK, G6PC2 and MTNR1B modulated the fasting glucose levels in the normoglycaemic population while SNPs from G6PC2 and GCKR was associated with type 2 diabetes." (PMID 20668700, 2010). "Meanwhile, GCKR polymorphisms were also shown to be associated with metabolic traits like fasting glucose and, modestly, type 2 diabetes." (PMID 19503597, 2009). "With the completion of the Human Genome Project and advances in next-generation sequencing, numerous studies have identified significant associations between GCKR variants and metabolic diseases, including type 2 diabetes, non-alcoholic fatty liver disease (NAFLD), and familial hypertriglyceridemia." (PMID 41150798, 2025). "Interestingly, GCKR variants exhibit a distinct relationship with type 2 diabetes (T2D) relative to other metabolic disorders." (PMID 41150798, 2025). "The GCKR locus is one of ∼240 loci that associate with blood glucose or type 2 diabetes risk." (PMID 37031802, 2023). "GCKR variants were related to glucose levels, insulin resistance, and type 2 diabetes." (PMID 35881683, 2022). "Moreover, three more variants were found in subject A, two VUS in the genes APOB and PKP2, and one likely pathogenic variant in the gene GCKR; this variant has been associated with a higher risk of type 2 diabetes." (PMID 36426223, 2022).
type 2 diabetes (continued). "Furthermore, the GCKR p.Leu446Pro variant (rs1260326[T]) associates with a lower risk of type 2 diabetes (Ncases = 36,710, Ncontrols = 663,962; OR = 0.94 [0.93–0.96], P = 1.4 × 10−10)." (PMID 33536631, 2021). "GCKR (rs780094) was first found to be associated with type 2 diabetes in Caucasians." (PMID 23990951, 2013). "In line with this, the GCKR gene sequence variant (rs780094) has been found consistently associated with increased serum triglycerides, decreased insulin resistance and protection from type 2 diabetes." (PMID 22724004, 2012). "The G allele of GCKR rs3817588 was associated with higher odds of type 2 diabetes (OR = 1.21)." (PMID 21569451, 2011). "Several intronic and an exonic (rs1260326P446>L) variant in the GCKR gene, within a large region of linkage disequilibrium on chromosome-2, associate with raised blood triglycerides and cholesterol and with increased risk for fatty liver disease but with decreased risk for Type 2 diabetes." (PMID 37031802, 2023). "Therefore, the activation of specific pathways (such as those that increase circulating BCAAs or short-chain, highly saturated triglycerides) may typically increase type 2 diabetes risk, except when such activation is caused by GCKR." (PMID 27898682, 2016). "In addition, IGF2BP2 and GCKR have been identified by several meta-analyses as risk genetic variants for Type 2 Diabetes with effects in WHR." (PMID 25852736, 2015). "Therefore, the proportion of IFH and IPH adds to the debate over whether GCKR is a susceptibility gene for type 2 diabetes in Han Chinese." (PMID 23990951, 2013). "Both common and rare GCKR variants have been linked to hypertriglyceridemia, NAFLD, and type 2 diabetes, underscoring their broad impact on human metabolic health." (PMID 41150798, 2025). "Several of the lipid‐associated genic hits like CETP, GCKR, and GLP1R are known to function in lipid metabolism, glucose metabolism, type 2 diabetes, and insulin resistance." (PMID 40665476, 2025). "For example, CRISPRa was used to activate the upstream intronic locus near the GCKR gene, and its involvement in type 2 diabetes (T2D) was confirmed." (PMID 39726634, 2024). "In the analysis with eight SNPs, we included variants in both the GCKR gene and the BDNF gene known to be associated with type 2 diabetes and body mass index (BMI) and smoking behaviour, respectively." (PMID 35679582, 2023). "Given the role of glucokinase in the development of maturity-onset diabetes of the young GCK_MODY or MODY_2 (MIM # 125851), mutations in GCKR have been considered to be associated with MODY_2." (PMID 38162681, 2023). "Converse risks for Type 2 diabetes and liver disease through the same GCKR variant has implications for therapies targeting GKRP or glucokinase for type 2 diabetes." (PMID 37031802, 2023). "To satisfy the independence assumption, we excluded the genetic variants located on the GCKR or FADS1 genes as previously, because these genes are strongly associated with other traits relevant to type 2 diabetes." (PMID 36624450, 2023). "The loci identified in the GD GWAS also included known genes affecting both type 2 diabetes and GD—GCKR, MTNR1B, and TCF7L2, as well as the MHC region." (PMID 36553520, 2022). "Glucokinase regulatory protein plays a critical role in hepatic glucose uptake and metabolism and is a drug target for type 2 diabetes." (PMID 30237882, 2018). "Noticeably, carriers of the validated type 2 diabetes risk allele G of GCKR showed lower risk of IPH; therefore the A allele of GCKR was defined as the risk allele in further joint study." (PMID 23990951, 2013). "In the present study, we confirm that the G allele of rs780094 in GCKR is associated with increased FPG and lower TG levels in newly diagnosed type 2 diabetes of Han ancestry." (PMID 23990951, 2013). "Association between GCK, GCKR, G6PC2 and MTNR1B variants and type 2 diabetes in the Chinese population." (PMID 20668700, 2010).
type 2 diabetes (continued). "Among the four genes studied, we found only GCKR rs780094 and G6PC2 rs16856187 affected type 2 diabetes risk in our samples." (PMID 20668700, 2010). "We found GCKR rs780094 and G6PC2 rs16856187 showed evidence for association to type 2 diabetes (p = 5.25×10−5 and 0.0021, respectively)." (PMID 20668700, 2010). "SNP rs1260326 of GCKR is well established to be associated with non-alcoholic fatty liver disease and type 2 diabetes, but not in sepsis." (PMID 41608459, 2026). "Our finding of glucokinase regulatory protein (GCKR) was also consistent with a previous study showing that GCKR variability may play a pathogenetic role in both type 2 diabetes and CKD." (PMID 38898508, 2024). "Variants in GCKR, including rs1260326, have been associated with higher glucose, insulin resistance and type 2 diabetes in non-gravid cohorts." (PMID 32556615, 2020). "Of these loci, only GCK, MTNR1B, DGKB, GCKR, ADCY5 and PROX1 (besides TCF7L2 and SLC30A8) were associated with type 2 diabetes at genome-wide significance levels, with several others (but not all) showing a consistent trend but not meeting the same stringent statistical threshold." (PMID 22984506, 2012). "It is interesting to note that, excluding the TCF7L2 SNP, three of the four variants most strongly associated with type 2 diabetes in the MAGIC study (MTNR1B rs10830963, PROX1 rs340874 and GCKR rs780094) have odds ratios of less than one in our South Asian populations." (PMID 21949744, 2011). "Although GCKR was also associated to triglyceride levels, its association to type 2 diabetes was independent of triglyceride (p = 0.0001 after adjusting age, gender, BMI and triglyceride levels as the confounding factors)." (PMID 20668700, 2010). "The glucokinase regulatory protein (GCKR) regulates glycogen metabolism and insulin secretion, and the GCKR rs1260326 is a putative single nucleotide polymorphism (SNP) associated with metabolic disorders including nonalcoholic fatty liver disease (NAFLD) and type 2 diabetes mellitus (T2DM)." (PMID 37829557, 2023). "Genetic variants at KCNQ1 rs151290, KLF14 rs972283, GCKR rs780094 and MTNR1B rs10830963 have been associated with type 2 diabetes mellitus (T2DM), but the results are contradictory in Chinese populations." (PMID 26927145, 2016). "The evidence that the variants GCK rs1799884, GCKR rs780094, MTNR1B rs10830963 and G6PC2 rs560887, which are related to fasting plasma glucose levels, increase the risk of type 2 diabetes mellitus (T2DM) is contradictory." (PMID 23840762, 2013). "Recently, the MAGIC study conducted a large-scale meta-analysis and provided convincing evidence that the GCKR rs780094 A allele was associated with lower fasting glucose and insulin levels, a lower HOMA-IR index, a higher triglyceride level, and a lower risk for type 2 diabetes." (PMID 21569451, 2011). "Therefore, the association of GCKR variants with fasting plasma glucose and type 2 diabetes is still not confirmed in a Chinese population." (PMID 21569451, 2011). "The GCKR rs1260326, substitutes proline to leucine at position 446 of amino acid (P446L), is a genetic risk factor associated with obesity-associated nonalcoholic fatty liver (NAFLD) and type 2 diabetes mellitus (T2DM) in different population." (PMID 37829557, 2023). "In the present study, genetic evidence, excluding the influences from FADS and GCKR, supports a protective effect of increasing POA levels on fasting glucose level and type 2 diabetes." (PMID 31690987, 2020). "Among the 25 potential pleiotropic genes, two genes, GCKR, and FADS1, were suggested to be pleiotropic genes for type 2 diabetes, obesity and dyslipidemia based on the results of previous studies." (PMID 30110382, 2018). "Furthermore, a synergistic effect between GCKR and type 2 diabetes on CAD risk cannot be ruled out." (PMID 30352097, 2018).
type 2 diabetes (continued). "Previous studies identified melatonin receptor 1B (MTNR1B), islet-specific glucose 6 phosphatase catalytic subunit-related protein (G6PC2), glucokinase (GCK) and glucokinase regulatory protein (GCKR) as candidate genes for type 2 diabetes (T2D) acting through elevated fasting plasma glucose (FPG)." (PMID 20628598, 2010). "SNPs from GCK, GCKR, G6PC2 and MTNR1B were genotyped in the Shanghai Chinese, including 3,410 type 2 diabetes patients and 3,412 controls." (PMID 20668700, 2010).